TTBK2 (tau tubulin kinase 2)
Diseases named in the same sentence as TTBK2 in open-access papers (continued):
Sharing a sentence is not in itself a finding about the gene and the disease.
spinocerebellar ataxia (10 papers, 2017 to 2026). "Future studies investigating these processes will be crucial for unraveling the pathogenic mechanisms of TTBK2 dysfunction and its role in the development of cerebellar ataxia." (PMID 41422144, 2025). "Loss of TTBK2 prevents ciliogenesis, and defective TTBK2 leads to severe pathologies including spinocerebellar ataxia and Alzheimer’s disease." (PMID 40279433, 2025). "More recently, some heterozygous missense variants in TTBK2 have been reported in patients presenting with cerebellar ataxia." (PMID 36892783, 2024). "Since loss-of- function mutation of Ttbk2 leads to spinocerebellar ataxia 11 and neuron-specific deletion of Ttbk2 induces loss of Purkinje cells, development of TTBK1-specific inhibitor such as ASO-Ttbk1, is necessary to avoid unwanted off-target effect." (PMID 37853497, 2023). "We also analyzed the co-expression network of those ataxia risk genes and revealed a central role of Eef2, Grid2, Tubb4a in the co-expression networks, while Ttbk2 and Bean1 have few interactions with other ataxia risk genes." (PMID 30690467, 2019). "Studies have shown that loss‐of‐function mutations in TTBK2 disrupt cilium formation, impair the connectivity and survival of cerebellar Purkinje neurons, and cause spinocerebellar ataxia, underscoring the critical link between TTBK2 dysfunction and central nervous system disorders." (PMID 41578860, 2026). "Additionally, TTBK2 missense variants were reported in patients with cerebellar ataxia but, in our understanding, additional studies are needed to validate their pathogenicity." (PMID 36892783, 2024).
Alzheimer disease (8 papers, 2014 to 2025). A progressive, neurodegenerative disease characterized by loss of function and death of nerve cells in several areas of the brain leading to loss of cognitive function such as memory and language. "One of the main targets of TTBK2 is the cytoskeletal tau protein; abnormal tau hyperphosphorylation is associated with neurofibrillary tangles (NFTs) formation and neurodegeneration in Alzheimer’s Disease." (PMID 36892783, 2024). "Aberrant TTBK2 activity was linked to the progression of the Alzheimer's disease." (PMID 26598643, 2016). "TTBK2 is expressed ubiquitously and can phosphorylate tau at sites identified in paired helical filament tau, a hyperphosphorylated tau variant found in the brains of Alzheimer’s disease (AD) patients." (PMID 26969328, 2016). "While efforts have been devoted to characterizing the impact of TTBK1 inhibition in diseases like Alzheimer’s disease and amyotrophic lateral sclerosis, TTBK2 inhibition has been less explored." (PMID 37059819, 2023). "Human TTBK kinases have been associated with neurodegeneration, where TTBK1 is thought to phosphorylate Tau protein and promote the progression of Alzheimer's disease and TTBK2 has been linked to another Tau‐related disease, spinocerebellar ataxia 11 (SCA11)." (PMID 28560849, 2017). "Interestingly, the two TTBK2-dependent phosphorylation sites in tau (Ser208 and Ser210) have been reported as elevated phosphorylation sites in Alzheimer’s disease brain." (PMID 36892783, 2024). "TTBK1 and TTBK2 were originally purified on the basis of their kinase activity on the microtubule binding protein tau at several pathological phospho-tau epitopes known to accumulate in Alzheimer's disease." (PMID 25473830, 2014). "Both TTBK1 and TTBK2 were initially identified as tau kinases and TTBK1 has been shown to phosphorylate tau epitopes commonly observed in Alzheimer’s disease and other tauopathies." (PMID 29409526, 2018).
ciliopathies (5 papers, 2015 to 2025). "It is currently not known whether and how these mutations affect the interaction between CEP164 and TTBK2 to give rise to the underlying ciliopathy." (PMID 34499853, 2022). "Mutation of TTBK2 may potentially be more serious than mutations of other proteins involved in ciliopathies because its heterozygous mutation results in SCA at the age as early as of 11 years old." (PMID 25950000, 2015). "A recent study linking ciliopathies to DNA damage response showed that TTBK2 is localized to the midbody between dividing cells." (PMID 25950000, 2015). "These symptoms are different from those of ciliopathies, suggesting differential roles of TTBK2 involved in cells." (PMID 25950000, 2015). "Although TTBK2 has a proven function in cilia formation, the phenotype caused by heterozygous TTBK2 truncating variants are not clearly typical of ciliopathies." (PMID 36892783, 2024). "Although TTBK2 has been implicated in ciliogenesis, the phenotypes caused by single heterozygous mutation of TTBK2 are not exactly characteristic of ciliopathies but instead of SCA11." (PMID 25950000, 2015).
melanoma (4 papers, 2015 to 2025). A malignant, usually aggressive tumor composed of atypical, neoplastic melanocytes. "Upregulation of TTBK2 is observed in kidney carcinoma and melanoma and is associated with resistance to the tyrosine kinase inhibitor sunitinib." (PMID 40424447, 2025). "In kidney carcinoma and melanoma, TTBK2 expression is associated with resistance to Sunitinib and cancer cell migration." (PMID 36685851, 2022). "Upregulated TTBK2 in kidney carcinoma and melanoma cell lines is correlated with resistance of the target therapeutic drug Sunitinib, while knockdown of TTBK2 in these cells increases Sunitinib sensitivity." (PMID 25950000, 2015). "TTBK2 downregulation sensitizes melanoma cells and renal cells to sunitinib." (PMID 36979179, 2023).
tauopathies (3 papers, 2014 to 2025). "Research has indicated that tau tubulin kinases TTBK1 and TTBK2, which are upregulated in tauopathies, have been shown to mediate the pathological phosphorylation of both tau and TDP-43, suggesting they act as molecular links converging on both proteins." (PMID 40722308, 2025). "To assess whether TTBK2 catalytic activity could drive tauopathy related phenotypes, we crossed hTTBK2-cat Tg C. elegans lines with tau(low) and tau(high) Tg lines." (PMID 29409526, 2018). "The identification of TTBK1 and TTBK2 as both tau and TDP-43 kinases indicates a possible shared mechanism for the initiation of TDP-43 proteinopathy and tauopathy in FTLD." (PMID 29409526, 2018). "No specific small molecule inhibitors targeting TTBK1 or TTBK2 has been reported to date, despite their potential roles contributing to tauopathies by hyperphosphorylating tau." (PMID 25473830, 2014).
frontotemporal dementia (2 papers, 2021 to 2022). Frontotemporal dementia (FTD) comprises a group of neurodegenerative disorders, characterized by progressive changes in behavior, executive dysfunction and language impairment, as a result of degeneration of the medial prefrontal and frontoinsular cortices. "CEP164 binds to TTBK2, a kinase that phosphorylates tau and contributes to neurodegeneration in frontotemporal dementia." (PMID 33861770, 2021).
medulloblastoma (2 papers, 2024 to 2025). A malignant, invasive embryonal neoplasm arising from the cerebellum. "Utilizing two spatially resolved transcriptomics from SHH patient-derived orthotopic xenograft medulloblastomas (PDOX MBs), we investigated the link between TTBK2 expression and the molecular characteristics of SHH-MB." (PMID 38879724, 2024).
brain tumor (1 paper, 2024). "Given the link between uncontrolled GNP proliferation and SHH-MB, our findings illuminate TTBK2 as a potential therapeutic target for this specific brain tumor subtype." (PMID 38879724, 2024). "Our results also highlight TTBK2 as a potential therapeutic target for this specific type of brain tumor." (PMID 38879724, 2024).
breast carcinoma (1 paper, 2022). "CTGF plays a vital role in chondrocyte proliferation, combined with the previous study on the role of TTBK2 in regulating the cell proliferation, together with ITGA2 and CTGF, TTBK2 may coordinate the adhesion and proliferation of the migrated breast cancer cells in the bone subsequent lesion." (PMID 35685372, 2022). "It suggests that upregulated DPP9, LRRC20 and TTBK2 together with downregulated TTC17, ZNF75D and CYTH2 may play pivotal role in the orchestrated adaptive homing of metastatic breast cancer cells in bone niche." (PMID 35685372, 2022).
cervical cancer (1 paper, 2023). A primary or metastatic malignant neoplasm involving the cervix. "TTBK2 inhibits the activity of the microtubule depolymerase of KIF2A through phosphorylation, thus promoting the migration of cervical cancer cells." (PMID 36979179, 2023).
Hydrocephalus (1 paper, 2018). Hydrocephalus is an active distension of the ventricular system of the brain resulting from inadequate passage of CSF from its point of production within the cerebral ventricles to its point of absorption into the systemic circulation. "Although the targeting strategy was designed to trap splicing of an early Ttbk2 exon, the homozygous gene trap mice (Ttbk2gt/gt) were viable past weaning, developing variably penetrant hydrocephalus and polycystic kidneys by 6 months of age." (PMID 30532139, 2018).
Joubert syndrome (1 paper, 2025). Joubert syndrome (JS) is characterized by congenital malformation of the brainstem and agenesis or hypoplasia of the cerebellar vermis leading to an abnormal respiratory pattern, nystagmus, hypotonia, ataxia, and delay in achieving motor milestones. "For example, although phosphorylation of CEP164 and CEP83 mediated by TTBK2 is essential for ciliogenesis, the complete spectrum of TTBK2 substrates, particularly in pathological conditions such as Joubert syndrome, has not been fully elucidated." (PMID 40433930, 2025).
malignant glioma (1 paper, 2019). A grade III or grade IV glioma arising from the central nervous system. "(2017) found that circ‐TTBK2, but not linear TTBK2, is upregulated in human malignant glioma." (PMID 30719845, 2019).
neuroblastoma (1 paper, 2014). Neuroblastoma (NB) is the most common solid, extracranial childhood tumor. "Likewise, we utilized SH-SY5Y cells, a human neuroblastoma-derived cell line, to determine the location of phosphorylated TDP-43 produced by TTBK2 transfection." (PMID 25473830, 2014).
proteinopathies (1 paper, 2018). "It remains unknown whether changes in TTBK1 and TTBK2 activity, abundance, and proteolytic processing influence tau- and TDP-43-proteinopathies." (PMID 29409526, 2018). "Surprisingly, the TTBK2/TDP-43 transgenic combination showed no exacerbation of TDP-43 proteinopathy related phenotypes." (PMID 29409526, 2018).
tumor (10 papers, 2017 to 2024). "Previous studies indicated that TTBK2 could phosphorylate tau and tubulin, which were implicated in tumor progression." (PMID 36685851, 2022). "From our analyses, DPP9 (Dipeptidyl Peptidase 9), LRRC20 and TTBK2 expressions were the top three upregulated genes that may be associated with the homing of the migrated tumour cells in the bone." (PMID 35685372, 2022). "For instance, inhibition of circ-TTBK2, functioned as miR-217 sponge, was found to restrain tumor proliferation via down regulating HNF1β and Derlin-1." (PMID 31895689, 2019). "The down-regulation of circ-TTBK2 together with the overexpressed miR-217 inhibited tumor growth in mice." (PMID 30583549, 2018). "Remarkably, knockdown of circ-TTBK2 combined with miR-217 overexpression resulted in the smallest tumor volume." (PMID 28219405, 2017). "Remarkably, the in vivo study demonstrated that the inhibition of circ-TTBK2 and restoration of miR-217 exhibited the lowest tumor volume and the longest survival tumor-bearing nude mice." (PMID 28219405, 2017). "Remarkably, circ-TTBK2 knockdown combined with miR-217 overexpression led to tumor regression in vivo." (PMID 28219405, 2017). "More importantly, we demonstrate that depletion of TTBK2 impairs SHH-MB cell proliferation, representing a potential therapeutic target for this type of tumor." (PMID 38879724, 2024). "Moreover, we have established a link between TTBK2 and SHH-type medulloblastoma (SHH-MB), a tumor characterized by uncontrolled GNP proliferation." (PMID 38879724, 2024).
cancer (6 papers, 2014 to 2024). A tumor composed of atypical neoplastic, often pleomorphic cells that invade other tissues. "TTBK2 has also been implicated in cancer progression, transporter stimulation, and TDP-43 accumulation, among other processes." (PMID 25950000, 2015). "Although none of the somatic loss-of-function mutations is linked to human diseases, these data suggest that TTBK2 loci are highly susceptible to somatic mutations and may be associated with human diseases related to cancer or neurodegenerative disorders." (PMID 24808823, 2014). "In conclusion, our findings support the notion that TTBK2 inhibition represents a potential anti-cancer strategy for SHH-MBs." (PMID 38879724, 2024). "Here, we review TTBK2's structure and its involvement in spinocerebellar ataxia, ciliogenesis, cancer, and other cellular activities." (PMID 25950000, 2015). "TTBK2 depletion inhibits SHH-MB proliferation, indicating that TTBK2 may be a potential therapeutic target for this cancer type." (PMID 38879724, 2024). "Reduction of TTBK2 also increases Sunitinib inhibition of cancer cell migration." (PMID 25950000, 2015). "TTBK2 has been reported to exhibit differential expression in cancer cells." (PMID 25950000, 2015). "TTBK2 may also be involved in anti-cancer drug resistance: TTBK2 increases the cell surface number of sodium-coupled glucose transporter (SLC5A1) in cancer cells and confers cell survival against anti-cancer drugs." (PMID 24808823, 2014). "It suggests that TTBK2 may promote the homing of metastatic cancer cells in the bone." (PMID 35685372, 2022). "Moreover, restoration of miR-217 expression reversed the circ-TTBK2-induced promotion of cancer progression, suggesting a reciprocal negative feedback between circ-TTBK2 and miR-217." (PMID 29147648, 2017).
neurodegenerative disease (3 papers, 2014 to 2020). A disorder of the central nervous system characterized by gradual and progressive loss of neural tissue and neurologic function. "Mutations within TTBK2 cause the adult-onset, neurodegenerative disease SCA11." (PMID 31934864, 2020). "Both TTBK1 and TTBK2 have been previously implicated in neurodegenerative diseases." (PMID 25473830, 2014).
TTBK2 also shares sentences with these, for which no sentence is quoted: Ataxia (3 papers); kidney carcinoma (3); cerebellar ataxia (2); holoprosencephaly (2); acquired ataxia (1); amyotrophic lateral sclerosis (1); autosomal dominant cerebellar ataxia (1); autosomal dominant disease (1); Boucher–Neuhauser Syndrome (1); central nervous system disorder (1); cerebellar degeneration (1); episodic ataxia type 6 (1); gastric cancer (1); hereditary ataxia (1); hereditary cerebellar ataxia (1); hereditary neurodegenerative disorder (1); lung adenocarcinoma (1); nephronophthisis (1); neurological disorder (1); non-small cell lung carcinoma (1); ovarian carcinoma (1); polycystic kidneys (1); spinal cord injury (1).